IL6 (interleukin 6)
Diseases named in the same sentence as IL6 in open-access papers (continued):
Sharing a sentence is not in itself a finding about the gene and the disease.
Arthritis (continued). "Our results demonstrated that the CFA-arthritis group recorded a significant increase in plasma IL-6 level compared to the normal control group." (PMID 36678557, 2022). "TNF-α and IL-6 are key cytokines that drive inflammation in arthritis; TNF-α levels were elevated in patients with loss-of-function mutations in the DNase II gene, and both TNFα and IL-6 levels were high in DNase II−/−Ifnar1−/− mice." (PMID 34901991, 2022). "Proinflammatory cytokines such as TNF-α, interleukin 1 (IL-1), and interleukin 6 (IL-6) are abundantly produced in the arthritis joints of SKG mice." (PMID 35148358, 2022). "Inhibition of S1P led to decreased serum levels of pro-inflammatory TNF-α, IL-1β, and IL-6 and reduced arthritis activity in previous in vivo experiments, allowing the assumption that S1P is a key regulator of TNF-α stimulated IL-1β and IL-6 release in RA." (PMID 35036874, 2022). "We measured CXCL1, CXCL5 IL-6, IL-8, IL-10, TNFα, and total IgG levels in the aliquots of set 1 and set 2 in eight arthritis patients." (PMID 34998422, 2022). "In arthritis, several cytokines, such as IL-1, IL-6, IL-8, IL-12, IL-17, TNF-α, and IFN-γ, are involved in almost all aspects of articular inflammation and destruction." (PMID 35280697, 2022). "In this study, rats with CIA were successfully developed and subsequently, the levels of TNF-α and IL-6 in rats significantly improved and pathological changes on arthritis obviously displayed." (PMID 34880764, 2021). "A recent study also showed that TLR7 deficiency led to K/BxN serum-induced arthritis reduction by imparing interferon regulatory factor 5 (IRF5) mediated IL-1β and IL-6 generation in macrophages and synovial fibroblasts, respectively." (PMID 34950033, 2021). "To investigate if cytokines other than TNF also affect LMC function, we treated cells with IL-6, an important cytokine for arthritis." (PMID 33602317, 2021). "In a mouse model of arthritis Pglyrp2 KO mice were partly protected against arthritis, and WT mice had higher levels of Il1b, Il6, and Tnf-α in the foot and a higher incidence of arthritis." (PMID 33833993, 2021). "TQ (10 mg/kg body weight) significantly downregulated the elevated level of Toll-like receptor (TLR) and other inflammatory cytokines (TNF-α, IL-1, and IL-6) in a Freund’s complete adjuvant (FCA)-induced arthritis rat in vivo model." (PMID 34067322, 2021). "Net gelatinolytic activities, IL-6 levels and local neutrophil counts in synovial fluids were important local biomarkers, in line with systemic disease parameters of arthritis." (PMID 34912337, 2021). "Immunohistochemistry analysis revealed that AJNR mainly acted via the inhibitory effects of IL-6-mediated matrix metalloproteinase-3 and -13 in both arthritis models." (PMID 34451873, 2021). "CD4+ T cells play a critical role in GPI-induced arthritis, and the effect of biological agents including anti-interleukin-6 (IL-6) receptor antibodies is similar to that found in RA patients." (PMID 34299252, 2021). "Here, we explored neutrophil extracellular trap (NET)osis in experimental models of arthritis and further investigated the effects of interleukin-6 (IL-6) inhibition in neutrophils and NETosis." (PMID 34299252, 2021). "Arthritis, as well as IL-6 concentration in serum, was significantly reduced, and the survival of PAD4 knockout neutrophils was impaired." (PMID 34299252, 2021). "Visual inspection and biochemical examinations including TNF-α, interleukin 6, and C-reactive protein were performed to assess arthritis severity during the treatment." (PMID 34880764, 2021). "In the 8-month-old mice, 1 mg of LPS orally given on day 3 after the type II collagen antibody cocktail injection (1.5 mg) induced arthritis within 24–48 hours and reached a plateau after 7-8 days with high serum IL-6 levels." (PMID 33833871, 2021). "Further investigations are needed to explore the relevance between the efficacy of anti-IL-6 mAb treatment and serum IL-6 levels with an arthritis animal model." (PMID 35126375, 2021).
Arthritis (continued). "The in vivo activity was evaluated using parameters like COX, TNF-α and IL-6 inhibition assay and arthritis score in Freund Adjuvant (CFA) models at a dose of 400 mg/kg b.w. per day of different fractions (hexane, chloroform, alcoholic)." (PMID 33919084, 2021). "Siltuximab and tocilizumab, targeting IL-6 and the IL-6R respectively, have been approved for the treatment of Castleman disease (siltuximab) and arthritis (tocilizumab)." (PMID 35118141, 2021). "The pharmacological or genetic blockage of GABAB-Rs in murine DCs inhibited their production of IL-6 and the priming of Th17 cells, and baclofen treatment alleviated murine collagen-induced arthritis." (PMID 33418884, 2021). "Another preclinical study showed that intragastric administration of L. casei prevented the development of Salmonella enterocolitis-induced arthritis and reduced expression of proinflammatory cytokines (e.g., IL-1β, IL-6, IL-17, IL-23, and TNF-α)." (PMID 34065638, 2021). "A recent study showed that TLR7 deficiency alleviated K/BxN serum-induced arthritis by imparing interferon regulatory factor 5 (IRF5) mediated IL-1β and IL-6 produced by macrophages and synovial fibroblasts, respectively." (PMID 34950033, 2021). "We stimulated TNFα-pretreated OA- and RA-SF with 10–11 to 10–14 M PK2 and measured the cell culture medium concentration of the arthritis-aggravating factors IL-6 and MMP-3 and arthritis-inhibiting factors TIMP-1 and OPG." (PMID 34526577, 2021). "Administration of IL-21 receptor Fc fusion protein (IL-21RFc), a neutralizing agent of IL-21 in the arthritis model, significantly diminished IL-6 and IL-17." (PMID 33673829, 2021). "We show decreased prevalence of arthritis in p110α−/−ΔT mice, with decreased IL-6 and IL-17A secretion and enhanced anti-CII IgG1 antibodies in response to CII." (PMID 34203838, 2021). "In this study, we demonstrated that a novel humanized anti-IL-6 mAb HZ-0408b potently binds to IL-6, specifically inhibits IL-6 signaling, and can ameliorate established arthritis in CIA cynomolgus monkeys." (PMID 35126375, 2021). "The same group subsequently made similar observations in patients with AOSD, where IL-18-dominant patients had higher ferritin levels but a lower frequency of arthritis as compared to IL-6-dominant patients." (PMID 34635157, 2021). "In a murine model of collagen antibody-induced arthritis, arthritis scores and serum IL6 production of GRK5 knockout (GRK5-/-) mice were significantly lower than those of wild-type mice." (PMID 34006987, 2021). "In a type II collagen-induced arthritis rat model, MT exerted its anti-arthritis effects via down-regulation of pro-inflammatory cytokines and proteins (IL-6, IL-8, IL-1β, IL-17A, and TNF-α) and down-regulation of NF-κB." (PMID 33041782, 2020). "ELISA and qRT-PCR analysis showed that the induction of arthritis caused a significant increase in the levels of TNF-α, IL-1β, and IL-6 compared to the healthy group." (PMID 32401927, 2020). "Inflammatory mediators in arthritis, such as prostaglandin IL-1β, IL-6, and TNF-alpha, directly affect the lymphatic function and reduce the frequency of lymphatic pumps." (PMID 32280355, 2020). "Further, systemic inflammation, like what occurs in arthritis and other chronic musculoskeletal pain, results in producing inflammatory cytokines, such as plasma interleukin 6 and tumor necrosis factor-alpha." (PMID 33066753, 2020). "On the other hand, serum TNF-α, IL-6, and IL-17 levels were lower (36%, 29%, and 41%, respectively) in the MG group when compared with the arthritis group (P < 0.001 for all three)." (PMID 32659877, 2020). "The effects of Pg 33277 on the production of IL-6 and arthritis score showed similar trends to those of Pg W83, suggesting that both stains of Pg can augment the pathogenic outcomes of RA." (PMID 33076980, 2020).
Arthritis (continued). "We saw an arthritis-associated inflammation in case of static isotropic tensile strain, as the proinflammatory markers (TNF-α, IL-1β, IL-6, COX-2) were significantly upregulated." (PMID 32485947, 2020). "The primary cytokines required for inducing arthritis in autoimmune models are IL-1β, IL-6, IL-17A, TNF, GM-CSF, and RANKL." (PMID 32792961, 2020). "On the one hand, some pro-inflammatory cytokines, such as tumor necrosis factor-α (TNF-α), interleukin (IL)-6, and IL-1, facilitate the development of arthritis." (PMID 32958016, 2020). "Cytokines that are produced locally in the joint during arthritis, like IL-1, TNFα, IL-6, and IL-17, have been shown to modulate neurons." (PMID 32854769, 2020). "IL-6 and IL-β are innate immunity cytokines which have an important role in the pathogenesis of arthritis, by their chemotaxis and osteolytic capacities." (PMID 32849501, 2020). "Based on this principle, several researchers have started to use an anti-arthritis drug, tocilizumab, for its anti-IL-6 action." (PMID 32471083, 2020). "HMGB1 can induce the release of tumor necrosis factor-α (TNF-α), interleukin-1β (IL-1β), interleukin 1 (IL-1) and interleukin 6 (IL-6) and it controls the initiation and development of inflammation in various experimental arthritis models." (PMID 32709223, 2020). "Combination of CK and MTX was superior to CK alone or MTX alone in reduction arthritis signs of AA rats, and in reduction of pro-inflammatory cytokines IL-6 and IL-17." (PMID 33198544, 2020). "Up‐regulation of the antagonists of IL‐1 superfamily and down‐regulation of the pro‐inflammatory cytokine IL‐6 also support novel anti‐inflammatory and possibly disease‐modifying effects of mPGES1 inhibitors in arthritis." (PMID 32449517, 2020). "On the other hand, IL-6 promotes differentiation of pro-arthritis Th17 cells, blocks generation of the Treg cells, and triggers systemic inflammatory processes in RA." (PMID 32358783, 2020). "The significant decrease in the levels of TNF-α, IL-1β, and IL-6 confirmed a positive effect of rhoifolin on alleviating inflammation in CFA-induced arthritis." (PMID 32401927, 2020). "During this process, cytokines, such as TNF and IL-6, also play a critical role in the pathogenesis of inflammation in arthritis." (PMID 32958016, 2020). "The finding is of particular interest because it reveals that the recently recognized inducible expression of TRPA1 in human osteoarthritic chondrocytes is involved in increased IL-6 production, characteristic for the pathogenesis of arthritis." (PMID 33374841, 2020). "It has also been observed that the serum levels of several arthritis-associated or inflammation-associated cytokines, such as TNF, IL-1β, IL-6, and monocyte chemoattractant protein-1 (MCP-1), were augmented." (PMID 32958016, 2020). "Further, FMT from Pg-inoculated experimental arthritis mice reproduced donor gut microbiota and resulted in severe joint destruction with increased IL-6 and CP production in joint and intestinal tissues." (PMID 33076980, 2020). "IL-6 has been implicated in a variety of inflammatory diseases, but is perhaps best studied in the context of arthritis, a condition that can be effectively treated via blockade of IL-6 signaling." (PMID 31156640, 2019). "Mice treated with acarbose also showed a significantly decreased level of IL-6 in mice treated at arthritis induction (P < 0.05)." (PMID 32116681, 2019). "In animal models of arthritis, including antigen-induced arthritis (AIA), collagen antibody-induced arthritis (CAIA), and collagen-induced arthritis (CIA), IL-6 has been implicated as a key factor in peripheral pain mechanisms." (PMID 32047493, 2019). "In the case of IL-6, trans signaling is thought to be a critical mechanism by which IL-6 promotes disease pathogenesis, particularly arthritis and colorectal cancer." (PMID 31156640, 2019).
Arthritis (continued). "Like Enbrel, MTX also efficiently reduced the progression and severity of arthritis, presumably by reducing the levels of pro-inflammatory mediators such as IL-1, IL-6, TNF and prostaglandins." (PMID 30665457, 2019). "IL-6 appears to promote arthritis primarily via trans signaling, likely because synovial fibroblasts and activated CD4+ T cells do not express sufficient IL-6R to respond to IL-6 alone." (PMID 31156640, 2019). "Previous investigation of circulating lymphocytes from early arthritis patients revealed constitutive pSTAT3 levels to be higher, and correlate with paired serum IL-6 concentration more strongly, in CD4+ T cells than in CD8+ T-cells or B-cells." (PMID 31333666, 2019). "Current treatment of RA aims to block pro-inflammatory effector cytokines such as TNFα and IL6, which are produced in the synovium and trigger arthritis." (PMID 31001257, 2019). "When focusing on the ice-treated microcrystal-induced arthritis patients (N = 19), the decrease in synovial IL-6 protein levels became statistically significant, while this decrease was non-significant in RA and SpA patients." (PMID 31362785, 2019). "For example, mice with ALOX15, an isoform of ALOX8, knocked out had arthritis, with increased levels of IL-6 and IL-1β as compared with their wild-type controls, and the level of KC was correlated to their body weight loss." (PMID 31013822, 2019). "An example of mechanism-based therapy of arthritis in PID uses blockade of IL-6 signaling with tocilizumab for patients with STAT 3 gain-of-function (GOF) mutation and augmented IL-6 pathway." (PMID 31334206, 2019). "Mice treated with acarbose significantly reduced IL-9 (P < 0.05) and IL-6 (P < 0.001) while miglitol reduced IL-9 (P < 0.05) compared with mice gavaged with water alone in the protocol of treatment starting before arthritis induction." (PMID 32116681, 2019). "Active arthritis is rarely observed in iMCD; therefore, the activation of T cells with increased IL-6 levels was considered to contribute to the development of arthritis in this case." (PMID 31045763, 2019). "IL-6 is a pleiotropic cytokine with a pivotal role in the pathophysiology of arthritis and pain sensitization through increasing neuronal calcium mobilization, action potential generation, and ion channel sensitization." (PMID 32047493, 2019). "Our current results indicated that the IL-6 rs1800795 (-174 G>C) mutation is not only related to higher KOA risk and higher disease severity, but also to higher severity of arthritis." (PMID 30635366, 2019). "The efficacy of both substances was assessed based on clinical arthritis signs, as well as cytokine (interleukin [IL]-17, IL-6, and interferon [IFN]-γ) levels in lymphoid tissues." (PMID 29389956, 2018). "Elevated TNFα and/or IL-6 levels promote minor joint dominant arthritis, and activation of T cells such as TH17 cells is required for RA pathogenesis." (PMID 30361689, 2018). "Here, we show that activation of IL-1 signaling promotes major joint dominant arthritis, and that upregulation of either of IL-6, IL-17 or Stat3, which also function in RA, was required for arthritic phenotypes seen in hIL-1 cTg mice." (PMID 30361689, 2018). "In the present study, E. gracilis Z and paramylon suppressed the onset of arthritis and decreased the secretion of cytokines including IL-17 and IL-6." (PMID 29389956, 2018). "Ziel war es, den zirkadianen Rhythmus von Interleukin-6 (IL-6) im Serum von Ratten mit kollageninduzierter Arthritis (CIA) zu untersuchen sowie die Sicherheit und Wirksamkeit von Methotrexat (MTX) bei herkömmlicher Gabe und per Chronotherapie zu vergleichen." (PMID 27900440, 2018). "For example, IL-6 is a key pro-inflammatory cytokine that promotes the differentiation of pro-arthritis Th17 cells, blocks the generation of anti-inflammatory Treg cells and triggers systemic inflammatory processes, such as infiltration of inflammatory cells." (PMID 29323140, 2018).
Arthritis (continued). "On the contrary, another set of reports showed that miR-451 was increased in the RA sera and T cells of RA patients, and that its levels correlated positively with serum IL-6 and arthritis severity." (PMID 30081592, 2018). "Increased values of serum IL-6 were observed in arthritic rats since the early stages of arthritis, confirming the systemic inflammatory component of this animal model." (PMID 29315314, 2018). "IL-6 was strongly overexpressed from day 10 with a peak of expression at day 12 (60-fold) and remained high during arthritis (25-fold) (p < 0.05)." (PMID 29472591, 2018). "It is generally accepted that IL-1 is the pivotal cytokine during the early and late stages, while TNF-α is primarily involved during the onset of arthritis, and IL-6 is released during the inflammatory process in an OA joint." (PMID 30340603, 2018). "Reduction in arthritis was accompanied by reduced levels of IL‐6 and the inflammatory marker alpha‐1‐acid glycoprotein in sera of animals treated with the TLR9 antagonist." (PMID 29992753, 2018). "The value of achieving rapid and broad suppression of pro-inflammatory pathways during the earliest phase of arthritis by blocking TNF or IL-6-mediated signalling has been demonstrated, for example leading to sustained remission in about a third of patients." (PMID 29206659, 2018). "Osteoarthritis (OA), an inflammatory form of arthritis, is characterized by synovial inflammation and cartilage destruction largely influenced by two key proinflammatory cytokines—interleukin-6 (IL-6) and tumor necrosis factor α (TNF-α)." (PMID 29316707, 2018). "The inflammatory cytokines TNFα, IFNγ, IL-6 and IL-17 have been shown to play crucial roles in the development of arthritis in the K/BxN model." (PMID 28882929, 2017). "A significant correlation was observed between IL-6, IL-17A as well as IL-1β hind paw gene expression levels and the corresponding hind paws arthritis score, and ankle diameter." (PMID 28759646, 2017). "Previous studies showed that PFS suppressed Freund’s Complete Adjuvant induced rat arthritis (AIA) by downregulating mRNA levels of IL-6 and TGF-β1 in vivo and reducing joint protein expression levels of phospho-STAT3 and IKKα." (PMID 28463993, 2017). "TNF, IL‐6 and IL‐1β blocking agents in RA patients resulted in a decline in disease severity and relief of arthritis symptoms." (PMID 29226077, 2017). "Since proinflammation cytokines such as IL-6 and TNF-α have a documented central role in the pathogenesis of arthritis, we further measured the levels of IL-6 and TNF-α under the same condition." (PMID 28706956, 2017). "In our study, IL-6 production was upregulated in the synovial fluid of mice 7 days after induction of arthritis." (PMID 28587618, 2017). "In the future, IL-6 inhibitors, such as tocilizumab, can be also envisaged to be associated with apoptotic cell infusion in order to prevent the antagonistic effect of IL-6, previously reported in mBSA-induced arthritis." (PMID 29062314, 2017). "We confirmed that 10 ng/ml TNF-α represents an appropriate concentration to induce the production and expression of TNF-α and IL-6 that are typical for a synovial response to early joint inflammation." (PMID 29348703, 2017). "In contrast, IL-6 expression in synovial tissues from SKG mice with mild arthritis was lower than that from SKG mice with severe arthritis." (PMID 28056105, 2017). "This greatly reduced disease incidence shows the potential of the early IL-6/IL-21 combination strategy over single cytokine inhibition in blocking arthritis development, with comparable efficacy as the positive control group receiving TNFα inhibitors." (PMID 28158305, 2017). "As pro- or anti-inflammation cytokines are often related to the pathology of arthritis, we also examined the secretion levels of IL-1β, IL-6, IL-17A, TNF-α and IL-10 in AA models." (PMID 28352114, 2017).